OR52E5 (olfactory receptor family 52 subfamily E member 5)
Description:
Odorant receptor.
Synonyms: OR11-56
Tractability: Antibody: UniProt places it where antibodies can reach, with medium confidence; UniProt predicts a signal peptide or a membrane-spanning region; its Gene Ontology location is reachable by antibodies, with medium confidence.
Gene: Protein-coding gene on chromosome 11 (5,893,208 to 5,902,730, forward strand). Ensembl gene ENSG00000277932.
Subcellular location: Cell membrane
Pathways (Reactome):
Sensory Perception: Expression and translocation of olfactory receptors
Gene Ontology:
Molecular function: olfactory receptor activity; G protein-coupled receptor activity
Biological process: detection of chemical stimulus involved in sensory perception of smell; G protein-coupled receptor signaling pathway; nervous system process
Cellular component: plasma membrane; membrane
Homologues: Orthologues: chimpanzee OR52E5 (87% identical), mouse Or52e5 (83% identical), rat Or52e5 (83% identical), rabbit OR52E5 (82% identical), tropical clawed frog or52m1 (40% identical). Paralogues in human: OR52E2 (64% identical), OR52E4 (64% identical), OR52E8 (64% identical), OR52E6 (61% identical), OR52J3 (54% identical), OR52E1 (53% identical), OR52H1 (50% identical), OR52D1 (49% identical), OR52N4 (49% identical), OR52B2 (48% identical), OR52R1 (48% identical), OR52B4 (47% identical), and 39 more.